ENSG00000256514 (novel protein)
Gene: Protein-coding gene on chromosome 11 (67,351,572 to 67,373,584, reverse strand). Ensembl gene ENSG00000256514.
Genetic constraint (gnomAD): Loss-of-function variants: 7 observed, 8.86 expected, observed/expected ratio (o/e) 0.79, 90% interval 0.45 to 1.47. That is too few expected variants to judge how well the gene tolerates losing a copy. Missense variants: 78 observed, 78.04 expected, observed/expected ratio (o/e) 1, 90% interval 0.83 to 1.21. Synonymous variants: 39 observed, 33.81 expected, observed/expected ratio (o/e) 1.15, 90% interval 0.89 to 1.51.